CD34 (CD34 molecule)
Diseases named in the same sentence as CD34 in open-access papers (continued):
Sharing a sentence is not in itself a finding about the gene and the disease.
tumor (continued). "To elucidate the potential mechanisms involved in tumor growth inhibition by TFAP2BshRNA in vivo, we also analyzed the expression of VEGF, PEDF and micro-vessel density marker CD34 in tumors by immunohistochemical staining and found that VEGF expression was inhibited and the mean MVD was reduced." (PMID 24766673, 2014). "Our results rule out the possibility of contamination of the CD34+ niche with tumor cells in auto transplantation." (PMID 24498265, 2014). "The expression of CD31, CD34 and VEGF in the combination group was lower than other groups, which indicated that the combination of resveratrol and As2O3 achieved a stronger inhibition of the tumor vascularity." (PMID 24901647, 2014). "Immunohistochemical study indicated that the tumor cells were positive for CD117 and CD34." (PMID 24527092, 2014). "The positivity of spindle-shaped KS tumor cells for CD105 and COX-2, first reported in our study, in correlation with CD34, VEGF, SMA, and c-KIT positivity, seems to suggest that KS, similar to other fibroblastic tumors, originates from the PMCs and is related to the VEGF secretion." (PMID 23936513, 2013). "However, HS presents negative markers of epithelial (epithelial membrane antigen or cytokeratin), melanocytic (CD34 or myeloperoxidase) and lymphoid (CD3 or CD20) neoplasms as in our case." (PMID 23668836, 2013). "FISH analysis of recurrent HCCs resected from patients with sex-mismatched liver allografts revealed that all CD31+ and CD34+ intratumoral ECs originated from the donor allograft rather than the tumor." (PMID 24138671, 2013). "By immunohistochemical staining, the tumour cells were positive for CD34, Bcl-2, and SMA and negative for desmin, S100, C-kit, and HMB-45." (PMID 24490095, 2013). "Both CD34 and SMA presented either focal or diffuse expression in the tumor cells." (PMID 23936513, 2013). "VEGF release might also induce the appearance of pericyte-like CD34+ VEGF-R1+ cells, which play mutually-supporting roles in tumor-vessel neoformation and stabilization, respectively." (PMID 24341512, 2013). "In a phase IB study, treatment with oral Vit D3 in patients with HNSCC was shown to reduce the number of immune suppressive CD34+ cells (CD11b+CD33+CD14−HLA-DR−), increase HLA-DR expression, and increase plasma IL-12 and IFN-gamma levels in vitro, which would favor an anti-tumor Th1 immune response." (PMID 23508517, 2013). "Subgroup analyses by ER/PR positivity status and tumor stage (I vs. II) at diagnosis did not reveal any consistent patterns in the changes in caspase-3 and CD34 levels in the green tea and control groups." (PMID 24380073, 2013). "Immunohistochemically, the tumor cells were focally positive for S-100 protein, but negative for desmin, CD34 and EMA." (PMID 24294990, 2013). "The most important feature in HPC is extensive irregular staghorn vascular pattern, Immunohistochemistry tumor cells showed vimentin and actin focal positivity and were negative for CD34." (PMID 24294990, 2013). "Endothelial cells of lumens expressed CD31, CD34 and D2-40, but the intraluminal tumor cells were negative for D2-40 (F)." (PMID 24063649, 2013). "Of the two cases whose tumor cells were not immunoreactive for the S-100 protein, one case was in our group, and his tumor cells were positive for CD34 and vimentin, suggesting the tumor is not conventional Schwann cell-derived MPNST." (PMID 24112233, 2013). "In the in vivo Lewis lung carcinoma (LLC)-tumor-bearing mice model, we showed that oral administration of phloroglucinol significantly inhibited tumor growth and angiogenesis as well as the mobilization of circulating EPCs, CD45−/CD34+ progenitor cells." (PMID 22496756, 2012). "Immunohistochemically, the tumor cells showed positive reactivity for vimentin, Ki-67, smooth muscle actin, and CD34, but negative staining for S-100." (PMID 23152982, 2012). "In our case, there was strong and diffuse expression for CD31 in almost all tumor cells, and CD34 expression was absent." (PMID 22943673, 2012).
tumor (continued). "The immunoreactivity of anti-CD34 antibody was located only on the cytoplasm of endothelial cells, and not on tumor cells or interstitial cells." (PMID 22208663, 2012). "We observed an increased area of CD31 and CD34-labelled cells in xenografts derived from MDA-MB-231-ARTN as compared to xenograft derived from MDA-MB-231-VEC tumors, indicating significantly increased tumor microvessel density." (PMID 23185544, 2012). "SP-positive HeLa cells formed one tumor per two injections with 1 × 104 cells and CD34 and CD133 positive cells remained nontumorigenic in both cell lines." (PMID 22284662, 2012). "Small vessel-like structures in the tumor that were PAS-positive but CD34-negative were to be VM channels." (PMID 23170850, 2012). "Immunostaining showed that the tumor was positive for the Vimentin, Bcl-2 and CD34, and was negative for S-100, desmin, CD68, and α–SMA." (PMID 23148444, 2012). "Immunohistochemical studies showed that the tumor cells were positive for S-100 and negative for c-kit, CD34, and smooth muscle actin." (PMID 22277785, 2012). "The proportion of C4d positive endothelium to overall vascularity (C4d / CD34) appears to rise along with the grade of the tumor, although no significance was achieved." (PMID 23199209, 2012). "At four weeks after tumor resection and I/R injury, immunostaining revealed a large number of CD34 positive cells in intrahepatic and lung metastatic tumor nodules in the control group." (PMID 22384233, 2012). "CD34 and CD31 are two endothelial cell markers often used in determining tumor vascular density." (PMID 23153292, 2012). "The tumor cells were negative for CD34, CK 5/6, CK7, CK20, S100, desmin, α–SMA, CD45, CD30, CD68 and HMB45." (PMID 22943673, 2012). "With immunohistochemical stains, tumor cells reacted positive for CD34, Bcl-2, and ki67 and negative for CD10, CD117, S100, and Desmin." (PMID 21819590, 2011). "Here we also found that irbesartan decreased the length of CD34+ endothelium in tumours and that this was the case regardless of cancer cell AT1R expression level." (PMID 21703011, 2011). "Neither cell size nor tumor CD34+ structures were significantly different between the treatment groups (data not shown)." (PMID 22018000, 2011). "With immunohistochemical stains, her tumor cells reacted positive for Bcl-2, CD34, and ki67 and negative for CD10, CD117, S100, and Desmin." (PMID 21819590, 2011). "Several kinds of monoclonal antibody were used to evaluate tumor cells immunohistochemically and included anti-Vimentin, CD31, CD34, cytokeratin (CK AE1/AE3, 34 β-E 12, 5/6, and CAM 5.2), desmin, α-smooth muscle actin (α-SMA), myoglobin, myogenin, and Ki-67 (MIB-1) antibodies." (PMID 21329505, 2011). "Immunohistochemical analyses indicated that many of the tumor cells were positive for vimentin, while tumor cells were negative for cytokeratins, desmin, S-100 protein, actins, c-kit, and CD34." (PMID 21288322, 2011). "L50 tumours grew more slowly, showed a strong decrease in cyclin B1, over-expressed collagen IV, and had reduced laminin 332, VEGF and CD34 levels, which, collectively, may have restricted cell division, cell adhesion and neoangiogenesis." (PMID 22107808, 2011). "In our case, the tumor cells were strongly positive for CD34, CD99, Bcl-2, and vimentin and negative for smooth muscle actin (SMA), CD31, cytokeratin, S-100, CD117, and epithelial membrane antigen (EMA)." (PMID 21443810, 2011). "Immunohistochemically, the tumor cells showed strong vimentin immunostaining in all three cases and were positive for CD34 in two cases but negative for EMA and S-100 protein." (PMID 22192457, 2011).
tumor (continued). "Although tumour cells that express PADI4 lacked CD34 signals, the enzyme is located in CD34+ mesenchymal cells in the stromal region of the tumour tissues." (PMID 20222985, 2010). "The HUVECs that were cocultured with the supernatants from Caki-1 and 786-O cells incubated with WP1066 showed reduced tubular formation, and our pathological assessment of the xenograft tumours showed that WP1066 reduced STAT3 activation and the length of CD34-positive microvessels." (PMID 20461084, 2010). "The lack of tumor cell expression of CD34 and TdT markers, as seen in this patient, is more common in precursor T-ALL than in precursor B-ALL." (PMID 19284608, 2009). "In the case of Kaposi sarcoma, diffuse CD34 positivity (in addition to focal CD117 positivity) led to misinterpretation; subsequent positivity for antibody to Human Herpesvirus 8 (HHV-8) led to reclassification of the tumour at Sarcoma Unit." (PMID 19503800, 2009). "Immunohistochemically, the tumor cells showed positive reactivity for CD117 and CD34." (PMID 19500398, 2009). "Hence, the anti-leukemic effect of acadesine on K562 cells and CD34+ progenitor was long-standing and thus, we decided to test this compound on CML tumor formation in mice." (PMID 19924252, 2009). "However, little CD45+, CD31+, CD34+, and VWF+ cells were detected among tumor endothelial-like cells." (PMID 18286204, 2008). "The tumor cell-derived vasculogenic progenitors or vascular endothelial-like cells, which were lining on vessel walls, were determined by anti-human CD45, CD31, CD34, or VWF." (PMID 18286204, 2008). "When we analysed blood samples from patients with a high tumor burden, i.e., metastatic NSCLC, we found significantly elevated gene expression levels of CD34 and KDR which may indicate an elevated number of CEC." (PMID 18755033, 2008). "Immunohistochemical analysis showed that the tumour cells expressed vimentin, but not smooth-muscle actin, CD34, or desmin." (PMID 18257933, 2008). "Several genes not previously related to CD133+/CD34+ cell expansion were identified, some of which known to have tumor suppressor activities." (PMID 17559657, 2007). "There were greater concentrations of microvessels stained brown by the anti-CD34 antibody in the tumor samples from the estrogen receptor-negative group compared to the estrogen receptor-positive tumors." (PMID 17718911, 2007). "As CD34 is not very specific for blood vessels, especially in tumour tissue, the combination with a specific lymphatic endothelium marker such as D2-40 is necessary to differentiate between LVI and BVI." (PMID 16670715, 2006). "Instead, we theorised that our analyses captured the progressive ‘endothelial-like switch’ of CD11c+ DCs within the tumour-conditioned media, so we termed these CD11c+CD45+ DCs expressing CD31 and CD34, and exhibiting morphological and molecular properties of endothelial cells, VLCs." (PMID 15785750, 2005). "CD34 is more sensitive and specific than factor VIII for staining endothelial cells induced by tumour neovascularisation but could also stain some lymphatic vessels." (PMID 12232748, 2002). "The absence of CD34 in extravascular structures of the tumor mass stands in clear contrast with the pronounced CD34 positivity seen in the stromal cells of juxtatumoral and transitional zone of the peritumoral skin, as well as moderate in the marginal, unaltered skin." (PMID 41597444, 2026). "The induced perinodular tumor stroma did not exhibit immunoreactivity to the CD34 antigen." (PMID 41597444, 2026). "Thus, we stained K14 and Ivl-derived tumours taken at clinical endpoint for CD34 but found no expression." (PMID 41507151, 2026). "Upon transformation of dysplastic nodules to HCC, CD34 expression undergoes dramatic amplification, with diffuse and strong (+++) sinusoidal staining becoming evident in more than 50% of sinusoidal cells regardless of tumor grade." (PMID 40941632, 2025).
tumor (continued). "TdT was positive in 20%–90% of the tumour cells, while CD34 was negative in the two cases examined." (PMID 41047873, 2025). "The tumor exhibits positivity for Vimentin, PR, and SMA, with negativity for PanCk, S100, Desmin, PSA, CK5/6, BCL2, MDM2, and Melan A. Additionally, the Ki-67 proliferation index is approximately 25 %, and CD34 highlights only the vascular walls without tumor cell positivity." (PMID 40686513, 2025). "Using scRNA-seq on tumor tissues from 12 treatment-naïve GBC patients (GBC1–12) and benign gallbladder tissues from six chronic cholecystitis patients (CC1–6), the authors isolated 8897 endothelial cells (endothelial markers: CD34, PECAM1, VWF) and subclustered them into eight endothelial subtypes." (PMID 41154806, 2025). "The tumor cells were CD34-positive and negative for desmin, SMA, and S100." (PMID 40391055, 2025). "Lack of CD31 and CD34 expression within tumor cells, but positivity within inner blood vessel endothelium, is consistent with a diagnosis of non-glioneuronal, non-vascular neoplasm; CD34 negativity in tumor cells is compatible with PA." (PMID 41458616, 2025). "Furthermore, the IHC test indicated that administration of tRF‐34‐antagomir also suppressed the expression levels of Ki‐67, N‐cadherin, Vimentin, and CD34 protein levels and increased the expression levels of DAB2IP and E‐cadherin in the xenograft tumour tissues." (PMID 40263693, 2025). "Finally, cancer-associated fibroblasts (CAFs), identified by their high expression of CAF markers, interacted with EPCs and CD34+ Pro-B cells via CXCL12/CXCR4, promoting tumor progression and angiogenesis, as found in many tumor studies where CAFs promote tumor invasion via CXCL12/CXCR." (PMID 40990011, 2025). "Immunohistochemistry revealed that the tumour cells were positive for vimentin and SMA expression, focal expression of calponin and CD10, and weak expression of β-catenin, with no expression of CD117, DOG-1, desmin, caldesmon, HMB45, ALK, CD34, S-100, CK, or SOX10." (PMID 41357577, 2025). "In addition, CD34-positive lymphatic vessels observed in the deepest areas of tumor invasion have not been reported in Japan, with initial reports indicating that they are neoplastic lymphatic vessels." (PMID 40243510, 2025). "Humanized mouse models offer a partial solution by engrafting immunodeficient mice with human CD34+ hematopoietic stem cells, peripheral blood mononuclear cells (PBMCs), or humanized-bone marrow, liver, thymus (Hu‐BLT), enabling the evaluation of human immune-tumor interactions." (PMID 41013723, 2025). "Additionally, this group exhibited significantly lower expression of Ki67 and CD34 compared to other groups, suggesting that the DCM@OPR + L group could effectively suppress tumor growth." (PMID 40102383, 2025). "In addition, CD34-positive lymphatic vessels observed in advanced areas of tumor invasion have not been reported in Japan, but there are reports that they are neoplastic lymphatic vessels, and further investigation is needed." (PMID 40243510, 2025). "Together, these data support an integrated approach in which tumor size and Ki-67—interpreted alongside CD117, DOG1, and CD34, and complemented by molecular testing (KIT, PDGFRA, MMR status)—may contribute to diagnostic assessment and hypothesis generation for future risk stratification." (PMID 41465833, 2025). "TdT was positive in 50–90% of tumour cells, while CD34 was negative in all three cases." (PMID 41047873, 2025). "Immunohistochemically, CD34 and vimentin were positive while S100 was negative in tumor tissues." (PMID 39634408, 2024). "CD34 was mostly negative in tumor cell membranes but positive in vascular endothelium." (PMID 39432588, 2024).
tumor (continued). "Tumor cells express desmin and CD34 but are negative for CD99, Bcl-2, and STAT6." (PMID 39206171, 2024). "The attenuating effect of CBD on MCAM, VE-cadherin, and Endoglin expression and its capacity to increase CD34+ ECs could therefore be a contributory factor in the anti-angiogenic anti-tumor effect described for CBD, while also increasing CD34+ endothelial progenitor cell-mediated repair." (PMID 39518030, 2024). "CD34, D2-40, and S100 were used to confirm that tumor cells had no vascular or nerve invasion." (PMID 38902753, 2024). "In addition, CD34, EDIL3, and TPM3 were positively correlated with signaling pathways related to tumor immune response, invasion, and metastasis, particularly the IL6/JAK/STAT3, inflammatory response, TNF-α signaling via NF-kB, and epithelial-mesenchymal transition." (PMID 38840234, 2024). "SMA and CD34 colored blood vessels in the area of the tumor, but not the tumor cells." (PMID 37715931, 2024). "The tumour cells were also positive for CD34 but negative for S100." (PMID 38151535, 2024). "CD34 was negative in the tumor cells but positive in the vascular endothelium." (PMID 39432588, 2024). "Additionally, immunohistochemical examination revealed focal CD34 positivity, which was negative in the previous tumor samples of TUR material." (PMID 39768800, 2024). "In addition, we demonstrated different angiogenic pattern, in terms of micro vessel density (MVD) by CD34 immunohistochemical (IHC) staining and hypoxia, according to lung NET laterality, with right tumours presenting higher angiogenesis rates, and left tumours associated more commonly with hypoxia." (PMID 37775725, 2024). "In some studies, in addition to histological atypia (pleomorphism, necrosis, elevated mitotic index) and anaplasia, a gemistocytic cell component, lack of protein deposits and focal CD34 staining around tumour cells have been reported as significant predictors of adverse clinical course." (PMID 39294363, 2024). "We examined the mesenchymal stem cell markers (positive markers: CD73, CD90, CD105; negative marker: CD34) on the cultured and freshly isolated cells to search for hybrid cells in the culture and tumour tissue which can potentially lead to the development of diffusely infiltrating carcinoma." (PMID 37445938, 2023). "Hematoxylin and eosin (H&E) stain, both the PDSOs and matched patients’ tumor showed atypical spindle cell proliferation in LMS, LS, and DFSP patients.Both PDSOs and patients’ tumor displayed similar expression of markers, including Ki67, CD34, PARP1, VIM, and MMP9." (PMID 37686615, 2023). "Judah Folkman first suggested the idea that angiogenesis, which is closely related to tumor growth, is correlated with microvascular density, or the number of microvessels that can be counted in a sample tumor area using antibodies that are specific for endothelial cell markers (e.g., CD31, CD34)." (PMID 37370872, 2023). "Fucoidan showed negative reactivity for CD34 in tumor nodules." (PMID 36874031, 2023). "Some tumor sections were immunostained with ready-to-use primary antibodies against broad-spectrum cytokeratin (CK), vimentin, calretinin, Wilms tumor gene-1 (WT-1), D2–40, Paird box 8, synaptophysin, chromogranin-A, inhibin-α, S-100, Melan-A, HMB45, CD34, and Ki-67 (Maixin, Fuzhou, China)." (PMID 38115250, 2023). "In this case, the tumor cells strongly expressed vimentin but they were negative for CD34." (PMID 36134098, 2022). "A wide range of immunohistochemical stainings were performed, such as CD68, SMA, desmin, EMA, mucin 4, SOX10, S100 and CD34, from which we could not deduce a specific differentiation line of the tumor cells." (PMID 35645621, 2022). "In addition, immunohistochemical staining of the vascular endothelial cell marker CD34 revealed higher numbers of blood vessels at the ablation boundary in the IRFA group, whereas sporadic blood vessels were observed under the tumor capsule in the control group." (PMID 35033089, 2022).